GATM (glycine amidinotransferase)
Diseases named in the same sentence as GATM in open-access papers (continued):
Sharing a sentence is not in itself a finding about the gene and the disease.
Failure to thrive (1 paper, 2018). Failure to thrive (FTT) refers to a child whose physical growth is substantially below the norm. "L-Arginine:glycine amidinotransferase and GAMT deficiency in transgenic mice leads to Cr-dependent failure to thrive with reduced body weight and length." (PMID 30013483, 2018).
leukemia (1 paper, 2024). A malignant (clonal) hematologic disorder, involving hematopoietic stem cells and characterized by the presence of primitive or atypical myeloid or lymphoid cells in the bone marrow and the blood. "The role of CKB or GATM in the mediation of TATA‐induced anti‐leukemia effects warrants future study." (PMID 39049685, 2024).
preeclampsia (1 paper, 2023). Preeclampsia is a hypertensive disorder of pregnancy that is characterized by new-onset hypertension with proteinuria presenting after 20 weeks of gestation, and depending on mild or severe forms may initially present with severe headache, visual disturbances, and hyperreflexia. "The elevated mRNA expression of GATM was identified in the placenta of patients with preeclampsia." (PMID 36833425, 2023).
sarcopenia (1 paper, 2025). Progressive decline in muscle mass due to aging which results in decreased functional capacity of muscles. "For example, in primary sarcopenia, ST detects IGF1 downregulation in Type I fibers together with DST, GATM, and PLIN4 upregulation in Type II fibers, indicating parallel anabolic failure in slow fibers and stress-induced cytoskeletal and metabolic remodeling in fast fibers." (PMID 40718353, 2025).
X-linked creatine transporter deficiency (1 paper, 2025). "These include X-linked creatine transporter deficiency (CTD), guanidinoacetate methyltransferase (GAMT) deficiency, and l-arginine:glycine amidinotransferase (AGAT) deficiency." (PMID 40078706, 2025).
cancer (12 papers, 2016 to 2024). A tumor composed of atypical neoplastic, often pleomorphic cells that invade other tissues. "The GATM gene encodes glycine amidinotransferase, catalyzing the rate-limiting step in the synthesis of creatine, which plays a pivotal role in cancer progression and immunotherapy." (PMID 35625960, 2022). "GATM and MGST1 have been identified as novel biomarkers implicated in the progression of both HCM and cancer." (PMID 39160643, 2024). "uncovered that GATM‐mediated creatine synthesis can potentiate cancer metastasis and diminish survival in mice." (PMID 39160643, 2024). "GATM was significantly correlated with most immune checkpoint genes among cancers, which was extraordinarily obvious in PRAD, THCA and UVM." (PMID 39160643, 2024). "GATM as the rate-limiting enzyme for creatine synthesis enhances cancer metastasis and shortens mouse survival by upregulation of Snail and Slug expression." (PMID 36319832, 2022). "Although MMP1, MMP10 and PTHLH were mainly up-regulated in the 21 cancer types, the other two members GATM and ARHGEF26, were primarily down-regulated." (PMID 34301206, 2021). "Although PTHLH, MMP1 and MMP10 were mainly up-regulated in the 21 cancer types, the rest of the members GATM and ARHGEF26, were primarily down-regulated with a few exceptions." (PMID 34301206, 2021). "In addition, H3K4me3 enrichment was also decreased at the promoters of Myc, WW domain-containing transcription regulator protein 1 (Wwtr1) and neuropilin 1 (Nrp1), which participate in cancer metastasis, after GATM knockdown." (PMID 37370109, 2023). "The exact mechanism by which creatine or GATM-attenuated cancer growth and related to immunotherapy is still unclear; however, a possible tumor-suppressive role of GATM was supported by the fact that low expression of GATM was associated with poor survival of patients with ccRCC treated with ICIs." (PMID 35625960, 2022). "Functionally, GATM and MGST1 are likely involved in xenobiotic metabolism and epithelial mesenchymal transition in a wide range of cancer types." (PMID 39160643, 2024). "We also found that glycine amidinotransferase (GATM), the rate-limiting enzyme for creatine synthesis, is up-regulated in GBM, which is reported to mediate de novo synthesis of creatine, and enhance cancer metastasis and shortens mouse survival." (PMID 36838582, 2023). "Among the module genes, BUB1, GATM, PLCE1, NEGR1, PTGER3 and SH3RF2 were differentially expressed in three or more cancer tissues." (PMID 28694494, 2017). "Application of the integrative modelling to cancer genes revealed a major role for MAT enzymes (MAT2B and MAT2A), as well as PHGDH and GATM—enzymes involved in serine and glycine metabolism, respectively." (PMID 27966532, 2016). "In addition, we revealed that GATM and MGST1 played significant roles in cancer by affecting several classic cancer hallmarks." (PMID 39160643, 2024). "DNA methylation might also impact the expression levels of GATM and MGST1 because four methyltransferases were significantly correlated with their expression among cancers." (PMID 39160643, 2024). "According to previous works and the novel findings in our work, we hypothesized that high GATM and MGST1 expression in HCM might promote cancer progression through xenobiotic metabolism and immune‐related signatures, and the detailed cause‐result relation needs to be further investigated." (PMID 39160643, 2024). "Thus, we also investigated the role of GATM and MGST1 among cancers." (PMID 39160643, 2024). "(ii) Glycine amidinotransferase (GATM), which catalyzes the rate-limiting step in the synthesis of creatine, is downregulated in both cancer and non-cancer cell lines." (PMID 32365991, 2020).
myopathy (12 papers, 2015 to 2025). A disease of the muscle in which the muscle fibers do not function properly. "Several disease-specific cis-eQTLs were also detected, one of which proved the correlation between a statin-related eQTL for the gene GATM (glycine amidinotransferase), that encodes the rate-limiting enzyme in creatine synthesis, and statin-induced myopathy." (PMID 30294342, 2018). "Deficiency of the GATM is associated with morbidities in humans, including myopathies." (PMID 35535239, 2022). "Reduced levels of creatinine biosynthesis, by the reduction of GATM (enzyme that is involved in creatine biosynthesis) expression, were related as a protective factor against muscular changes, such as myopathies, resulting from chronic use of statins." (PMID 31968556, 2020). "However, our study is the largest sample size of meta-analysis to investigate the association between GATM polymorphisms and SIM, and also the first one to perform subgroup analysis according to the severity of myopathy and comedications." (PMID 33051696, 2021). "Moreover, a polymorphism of the enzyme glycine amidinotransferase (GATM or AGAT, the enzyme that catalyzes the first step in the synthesis of creatine) is associated with a reduced incidence of statin myopathy." (PMID 31533334, 2019). "Although not related to fiber, a deficiency in the GATM gene is related to an autosomal-recessive disorder with varying symptoms including myopathy." (PMID 29670642, 2018).
tumor (12 papers, 2015 to 2025). "We also revealed that the novel gene GATM can be a potential tumor suppressor and/or can be associated with therapeutic efficacy in metastatic ccRCC treated by ICIs." (PMID 35625960, 2022). "Collectively, activation of GATM may represent an efficient therapeutic approach for ccRCC harboring the PBRM1 mutation under ICIs by regulating creatine metabolism to enhance antitumor T cell immunity in the tumor microenvironment." (PMID 35625960, 2022). "ALDH2, ADH1B, ALDH3A2, DPT, EPHX2, and GATM were down-regulated in the tumor tissues, which is consistent with the expression of hub genes in the GSE3189 and GSE46517 datasets." (PMID 38378847, 2024). "In vivo, g10947- and g10949-mediated GATM downregulation effectively suppressed primary tumour growth in a BALB/c nude mouse model." (PMID 37370109, 2023). "GATM is the rate-limiting enzyme in creatine biosynthesis in adipocytes, and adipose-selective ablation of GATM attenuated tumor growth." (PMID 37561190, 2023). "Tumours derived from GATM-knockdown cells expressed lower levels of Snai1, Cdh2 and Rhoa than tumours-derived from controls." (PMID 37370109, 2023). "In xenograft tumours, GATM knockdown suppressed the expression of MYC, HMGA1, and HMGA2, and GAA diet feeding stimulated their expression." (PMID 37370109, 2023). "In particular, the GATM gene showed a non-tumor-specific expression compared with that of the levels in tumor tissues in The Cancer Genome Atlas Kidney Renal Clear Cell Carcinoma (TCGA-KIRC) data (n = 607, p = 3.07 × 10−7) and GSE105288 (n = 43, p = 0.045)." (PMID 35625960, 2022). "In this study, low expression of GATM predicted poor survival rates, indicating that it functioned as a tumor suppressor in PDAC." (PMID 36319832, 2022). "GATM, ARHGEF26 and POU2F3 were associated with better survival, and were recognized as tumor suppressors." (PMID 34301206, 2021). "Furthermore, GATM upregulation inhibited CCA cell proliferation in vitro and GATM overexpression inhibited CCA tumour growth in vivo." (PMID 39859271, 2025). "For instance, GATM has been pinpointed as a potential tumor suppressor." (PMID 38002445, 2023). "Further analysis of the subtype 2 population demonstrated that GATM (glycine amidinotransferase), as a novel gene associated with PBRM1 mutation, plays a pivotal role in ccRCC by using a cell culture model, revealing tumor, suppressive-like features in reducing proliferation and migration." (PMID 35625960, 2022). "QRT-PCR showed that the expression of the ACTA2, C1QTNF9, DNAH8, GATM, LBP, and NGF were significantly downregulated in tumor samples." (PMID 36319832, 2022). "Notably, GATM and MGST1 were found to be highly expressed in various tumours and showed significant prognostic implications." (PMID 39160643, 2024). "The immunohistochemical (IHC) staining results showed that the GATM expression level was higher in PDAC tumours with a lymph node metastasis stage of N1 or N2 than in N0-stage PDAC, consistent with the results of TCGA analysis." (PMID 37370109, 2023). "In in vivo experiments, the creatine level was not decreased in tumours derived from cells with GATM knockdown compared to those derived from control cells." (PMID 37370109, 2023).
kidney disease (7 papers, 2013 to 2025). "Our results confirm previously identified associations of NEMG (NAT8, GATM, SLC22A2, WDR72, NOS3, AGXT2 and CPS1) with kidney disease and kidney function, providing new information that expands these associations to other kidney disease biomarkers." (PMID 38858654, 2024). "Other detected genes including SLC19A3, CTF1, and GATM are related to kidney diseases." (PMID 35464862, 2022). "Recently, we have described a previously unknown kidney disease in which unique aggregates of a mutant GATM protein form directly in mitochondria." (PMID 34349672, 2021). "There were 7 proteins that exclusively associated only with the kidney domain supporting their proximal role in kidney disease (e.g., A4GALT, PCK2, EFNA3, BTN3A2, IDI2, GATM, FAIM)." (PMID 41282674, 2025).
infection (2 papers, 2020 to 2024). The state of being infected such as from the introduction of a foreign agent such as serum, vaccine, antigenic substance or organism. "Based on these, we speculate that GATM may regulate RETNLA to affect M2 macrophage polarization during H1N1pdms infection." (PMID 38229736, 2024). "With regard to creatine metabolism, expression of creatine synthesis enzyme genes GATM and GAMT decreased as a result of Mtb infection, while the creatine transporter SLC6A8 and creatine kinase (brain-type, CKB) were increased, most notably in our M2 infection model." (PMID 32341411, 2020).
mitochondrial disease (1 paper, 2021). "The pathophysiology of the GATM-associated mitochondrial disease expands the spectrum of diseases associated with pathological protein aggregates." (PMID 34349672, 2021).
GATM also shares sentences with these, for which no sentence is quoted: cardiac hypertrophy (5 papers); cardiovascular disease (5); metabolic disorders (4); myocardial infarction (3); atherosclerosis (2); Becker muscular dystrophy (2); breast carcinoma (2); Cognitive impairment (2); developmental delay (2); ischaemic stroke (2); AGAT deficiency (1); anorexia nervosa (1); arrythmias (1); Atrophy (1); cerebral creatine deficiency syndrome-1 (1); cerebrovascular disease (1); cholangiocarcinoma (1); chronic kidney failure (1); Crohn disease (1); deficiencies (1); Fanconi renotubular syndrome 1 (1); focal epilepsy (1); GAMT deficiency (1); glioblastoma (1); glomerulosclerosis (1); Glucose intolerance (1); heart diseases (1); hypertrophy (1); hypophosphatemic rickets (1); Infertility (1).
A further 20 diseases each share a sentence with GATM in 1 paper.